FCGRT (Fc gamma receptor and transporter)
Description:
Cell surface receptor that transfers passive humoral immunity from the mother to the newborn. Binds to the Fc region of monomeric immunoglobulin gamma and mediates its selective uptake from milk. IgG in the milk is bound at the apical surface of the intestinal epithelium. The resultant FcRn-IgG complexes are transcytosed across the intestinal epithelium and IgG is released from FcRn into blood or tissue fluids. Throughout life, contributes to effective humoral immunity by recycling IgG and extending its half-life in the circulation. Mechanistically, monomeric IgG binding to FcRn in acidic endosomes of endothelial and hematopoietic cells recycles IgG to the cell surface where it is released into the circulation. In addition of IgG, regulates homeostasis of the other most abundant circulating protein albumin/ALB. (Microbial infection) Acts as an uncoating receptor for a panel of echoviruses including Echovirus 5, 6, 7, 9, 11, 13, 25 and 29.
Synonyms: FcRn; FcgammaRn; alpha-chain
Tractability: Small molecule: a structure with a bound ligand is known. Antibody: an approved drug acts on it; UniProt places it where antibodies can reach, with high confidence; UniProt predicts a signal peptide or a membrane-spanning region; its Gene Ontology location is reachable by antibodies, with medium confidence. PROTAC: its protein half-life has been measured; a small molecule that binds it is known. Other modalities: an approved drug acts on it.
Gene: Protein-coding gene on chromosome 19 (49,506,806 to 49,526,917, forward strand). Ensembl gene ENSG00000104870.
Subcellular location: Cell membrane; Endosome membrane
Gene Ontology:
Molecular function: IgG binding; protein binding; beta-2-microglobulin binding; peptide antigen binding
Biological process: IgG immunoglobulin transcytosis in epithelial cells mediated by FcRn immunoglobulin receptor; immune response
Cellular component: endosome membrane; external side of plasma membrane; plasma membrane
Genetic constraint (gnomAD): Loss-of-function variants: 13 observed, 29.26 expected, observed/expected ratio (o/e) 0.44, 90% interval 0.29 to 0.71. The upper end of that interval is the gene's LOEUF score, 0.71, which puts it in group 2 of 6, group 1 being the genes least tolerant of losing a copy. Missense variants: 433 observed, 449.34 expected, observed/expected ratio (o/e) 0.96, 90% interval 0.89 to 1.04. Synonymous variants: 227 observed, 205.25 expected, observed/expected ratio (o/e) 1.11, 90% interval 0.99 to 1.24.
Homologues: Orthologues: macaque FCGRT (97% identical), chimpanzee FCGRT (93% identical), macaque FCGRT (90% identical), dog FCGRT (80% identical), pig FCGRT (74% identical), mouse Fcgrt (67% identical), rat Fcgrt (65% identical), rabbit FCGRT (65% identical), guinea pig FCGRT (59% identical), zebrafish mhc1uba (23% identical), zebrafish mhc1uka (22% identical), zebrafish mhc1uma (18% identical). Paralogues in human: HLA-B (28% identical), HLA-C (27% identical), HLA-F (27% identical), HLA-A (27% identical), HLA-E (27% identical), HFE (25% identical), HLA-G (24% identical), MR1 (24% identical), AZGP1 (23% identical), MICA (21% identical), MICB (21% identical), CD1B (18% identical), and 10 more.
Diseases named in the same sentence as FCGRT in open-access papers:
FCGRT is named in the same sentence as 146 diseases in open-access papers, as found by Europe PMC text mining. Sharing a sentence is not in itself a finding about the gene and the disease. The quoted sentences say what the papers report.
colorectal cancer (8 papers, 2014 to 2024). A primary or metastatic malignant neoplasm that affects the colon or rectum. "In a murine model of spontaneous colorectal cancer, homozygous inactivation of FCGRT led to increased tumor progression and metastasis." (PMID 32368865, 2020).
hepatocellular carcinoma (6 papers, 2019 to 2023). A malignant tumor that arises from hepatocytes. "The association between poor prognosis in hepatocellular carcinoma and non-small cell lung cancer and FCGRT downregulation has also been reported." (PMID 38132243, 2023). "In hepatocellular carcinoma biopsies, overall downregulation of FCGRT has also been correlated with poor prognosis." (PMID 32368865, 2020). "In line, global methylation levels in the −1529 to −570 bp region correlates with FCGRT mRNA expression in cell lines derived from hepatocellular carcinomas." (PMID 31209240, 2019). "Basal expressions of FCGRT mRNA and FcRn protein were evaluated in the human hepatic cell lines HepG2 and SNU-475 (hepatocellular carcinoma), and in the cardiomyocyte cell line AC16 (SV40 transformed)." (PMID 31209240, 2019).
non-small cell lung carcinoma (6 papers, 2016 to 2023). A group of at least three distinct histological types of lung cancer, including non-small cell squamous cell carcinoma, adenocarcinoma, and large cell carcinoma. "Herein, we showed for the first time that FCGRT mRNA is down-regulated in non-small cell lung carcinoma (NSCLC) patients and that FCGRT mRNA levels in both NSCLC and adjacent non-cancerous tissues are independently positively correlated with prognosis." (PMID 27384673, 2016). "In the non-small cell lung cancer study, it was elucidated that higher levels of FCGRT mRNA expression in both cancerous and noncancerous tissues are associated with a favorable prognosis." (PMID 38132243, 2023).
breast carcinoma (5 papers, 2017 to 2024). "On the other hand, FCGRT downregulation has been documented in progressive breast cancer types, and the expression levels seem to depend on the disease stage and aggressiveness." (PMID 32368865, 2020).
echovirus infection (4 papers, 2022 to 2025). "These echovirus infections can be completely abolished in human cell lines after the knockout (KO) of one of the FcRn-encoding genes, FCGRT, and susceptibility was restored by complementation with FCGRT." (PMID 35862785, 2022).
lung carcinoma (4 papers, 2016 to 2025). "In order to reinforce our findings regarding the prognostic significance of FCGRT mRNA expression in lung cancer, we performed in silico analysis of FcRn expression." (PMID 27384673, 2016).
bladder cancer (2 papers, 2022 to 2023). "FCGRT was identified as the key neutrophil-related gene linked to an adverse prognosis of bladder cancer." (PMID 36980771, 2023). "Additionally, FCGRT was identified as the key neutrophil-related gene linked to an adverse prognosis of bladder cancer." (PMID 36339597, 2022).
glioma (2 papers, 2020 to 2025). A benign or malignant brain and spinal cord tumor that arises from glial cells (astrocytes, oligodendrocytes, ependymal cells). "The mRNA expression of APOBEC3C, FCGRT, GNG5, and SP100 was elevated in glioma, whereas the expression of ADAP2, ALOX5AP, and LRRC25 was low." (PMID 32431729, 2020).
schizophrenia (2 papers, 2017 to 2022). A major psychotic disorder characterized by abnormalities in the perception or expression of reality. "FcGRT mRNA was upregulated by 27.1% in high-inflammation biotype schizophrenia cases compared to control subjects (p = 0.02) and by 38.5% compared to low-inflammation biotype schizophrenia cases (p < 0.001)." (PMID 35841099, 2022). "Although levels of FcGRT protein were unchanged between control subjects and schizophrenia patients (either high- or low-inflammation biotypes), we found that FcGRT mRNA was increased in the midbrain from schizophrenia cases with the high-inflammation biotype." (PMID 35841099, 2022). "In contrast, FcGRT and FcGR3A mRNA levels were elevated in the midbrain from “high inflammation” schizophrenia cases (FcGRT; p = 0.02, FcGR3A; p < 0.0001) in comparison to low-inflammation patients and healthy controls, while FcGR2B mRNA levels were unchanged." (PMID 35841099, 2022). "Gene transcript levels of FcGRT, FcGR3A, and FcGR2B were detected in the midbrain of both schizophrenia cases and control subjects." (PMID 35841099, 2022). "We found the high-inflammation biotype schizophrenia cases demonstrated increased expression of both the IgG transporter, FcGRT, and one of the pro-inflammatory receptors, FcGR3A." (PMID 35841099, 2022). "As such, we propose that FcGRT protein turnover in the midbrain is increased in high-inflammation biotype schizophrenia cases." (PMID 35841099, 2022). "We found that IgG and FcGRT protein abundance (relative to β-actin) was unchanged in people with schizophrenia compared with controls irrespective of inflammatory subtype." (PMID 35841099, 2022). "The amount of FcGRT 60-kDa protein also did not significantly differ when comparing high-inflammation biotype schizophrenia cases, low-inflammation biotype schizophrenia cases, and control subjects (W = 2.62, p = 0.27), although the schizophrenia group showed increased variance compared to controls." (PMID 35841099, 2022).
kidney tumor (1 paper, 2022). "Four CTR score-related genes that associated with improved survival were downregulated in kidney tumor tissues relative to normal tissues in both public datasets and local ccRCC samples, with Fc gamma receptor and transporter (FCGRT) being the sole exception." (PMID 36479115, 2022).
melanoma (1 paper, 2023). A malignant, usually aggressive tumor composed of atypical, neoplastic melanocytes. "Co-expression and correlation profile of B2M with CD1D, CD1B, and FCGRT dissociates in melanoma patients following B2M expression loss." (PMID 37077920, 2023). "To evaluate whether the expression of CD1D, CD1B, and FCGRT is affected in a β2M-dependent manner in malignant melanoma, we first obtained the expression levels of all β2M-STRING-predicted interacting genes (n = 20) from the GDC-TCGA-SKCM study." (PMID 37077920, 2023). "We provide further evidence that epigenetic changes in the TME of melanoma tumors have a direct impact on B2M and an indirect impact on CD1D gene expression (through SPI1) but not on CD1B and FCGRT expression in melanoma patients from the TCGA dataset." (PMID 37077920, 2023).
metastatic melanoma (1 paper, 2023). A melanoma that has spread from its primary site to another anatomic site. "We evaluated whether the differential expression of B2M and its correlated genes (CD1D, CD1B, and FCGRT) is associated with poor responses to anti-PD1 in metastatic melanoma." (PMID 37077920, 2023).
infection (63 papers, 2013 to 2026). The state of being infected such as from the introduction of a foreign agent such as serum, vaccine, antigenic substance or organism. "All the data were analyzed using the model-based analysis of genome-wide CRISPR/Cas9 knockout (MAGeCK) method; FCGRT and B2M, the two genes encoding the FcRn subunits, were identified as the essential genes for E18 infection." (PMID 35862785, 2022). "Knockout of FCGRT and B2M, which encode the two subunits of FcRn, prevented infection by E18 and other echoviruses in the same physiological cluster." (PMID 35862785, 2022). "Subsequently, The FCGRT-knockdown PAMs or control cells were inoculated with PRRSV-2 sublineage 8.7 strain FJ (multiplicity of infection [MOI]=1) and then assessed by Western blot and 50% tissue culture infected dose (TCID50) assay, respectively." (PMID 39651859, 2025).
tumor (62 papers, 2014 to 2026). "With regards to the protective genes of FCGRT, it has been found to be responsible for encoding neonatal Fc receptor (FcRn), which participates in the transport and homeostasis of immunoglobulin as well as anti-tumor immunity." (PMID 32431729, 2020). "Up-regulation of FCGRT indicated activated cancer metabolism, immunosuppressive tumor environment, and dysregulated functional status of immune cells." (PMID 36339597, 2022). "Among them, Module2 (highly express RNASE1, C1QA, CD163, CD14, C1QC, FCGRT, and MS4A7) and Module10 (highly express APOC1, CTSB, CTSL, and TYROBP) are more likely to display the characteristics of tumor-associated macrophages (TAMs)." (PMID 35990663, 2022). "Taken together, our results show that FCGRT influenced the tumor immune microenvironment through various mechanisms and shaped an immunosuppressive context in general." (PMID 36339597, 2022). "For example, the evidence suggests that FCGRT may play a role in the antitumor immune recognition of tumor cells at an early stage of tumor growth." (PMID 39940693, 2025). "Moreover, FCGRT was found to participate in cancer metabolic reprogramming and mediate an immunosuppressive tumor microenvironment." (PMID 36339597, 2022). "We conclude that FCGRT mRNA expression may be a useful additional marker for immunoscoring, reflecting tumor immune system, and help in the decision-making process for NSCLC patients." (PMID 27384673, 2016). "We found that FcRn was mainly expressed by resident and tumor-infiltrating immune cells, in the lung, indicating that FCGRT mRNA level might reflect lung antitumor immune response." (PMID 27384673, 2016). "Considering the role of FcRn in immunosurveillance and tumorigenesis, the decrease in FCGRT mRNA expression might be an important biomarker of the molecular changes promoting lung carcinogenesis and tumor progression." (PMID 27384673, 2016). "In addition, we found FCGRT-mediated cancer metabolic reprogramming and tumor microenvironment remodeling, which could be used as a novel biomarker for ICIs therapy." (PMID 36339597, 2022). "Comparative analysis revealed tumor-specific upregulation of GLRX3, IL1RN, and TNFRSF4 (p < 0.001), contrasting with downregulation of FCGRT, UBN2, and WNT5B in EC versus normal tissues." (PMID 40722666, 2025). "Consistent with the RNA-seq data, the protein expression levels of FCGRT, and GNG5 were upregulated in tumor tissues when compared with the normal controls." (PMID 32431729, 2020). "Specifically, the NR3C2, ANPEP, and FCGRT genes were significantly upregulated in tumor tissues, while PIK3R1, MME, SCD, and SERPINE1 genes were notably downregulated." (PMID 41011246, 2025).
cancer (42 papers, 2013 to 2026). A tumor composed of atypical neoplastic, often pleomorphic cells that invade other tissues. "Despite its participation in cancer metabolic reprogramming, FCGRT also plays a role in cancer immunity." (PMID 36339597, 2022). "Two genes (MAGEA12, TRPC7) are up-regulated and one gene (FCGRT) is down-regulated in the metastases from the 4 cancer types with significant gene lists." (PMID 29254233, 2017). "The predictive value of FcRn for NSCLC patient survival was evaluated by analyzing FCGRT mRNA expression (high or low) in cancer tissues." (PMID 27384673, 2016). "It is speculated that FCGRT regulates cancer metabolism through the engagement of FcRn with albumin transport." (PMID 36339597, 2022). "Herein, we also found that FCGRT mRNA levels were associated with a favorable outcome and provided prognostic information independently from important clinic-pathological parameters, when it was assessed in the cancer or, intriguingly, in the non-cancerous tissue part." (PMID 27384673, 2016). "Thus FCGRT mRNA downregulation in both cancer and noncancer cells in nonsmall‐cell lung cancer can be associated with weaker antitumor response and shorter progression‐free survival." (PMID 32368865, 2020).
FCGRT also shares sentences with these, for which no sentence is quoted: autoimmune disease (49 papers); myasthenia gravis (38); Autoimmunity (12); malaria (10); pemphigus (9); viral infections (9); chronic inflammatory demyelinating polyradiculoneuropathy (7); immune thrombocytopenia (6); Arthritis (5); autoimmune encephalitis (4); autoimmune hemolytic anemia (4); diabetes (4); glioblastoma (4); hemophilia A (4); lupus (4); neurological diseases (4); pancreatic cancer (4); ZIKV infection (4); asthma (3); bullous pemphigoid (3); colitis (3); colon cancer (3); Hypoalbuminemia (3); infectious disease (3); multiple myeloma (3); pancreatic ductal adenocarcinoma (3); stiff-person syndrome (3); allergic disease (2); Allergy (2); bronchiectasis (2).
A further 101 diseases each share a sentence with FCGRT in 2 papers or fewer.